ENSG00000159239 (novel protein)
Gene: Protein-coding gene on chromosome 2 (74,393,836 to 74,421,662, reverse strand). Ensembl gene ENSG00000159239.
Genetic constraint (gnomAD): Missense variants: 634 observed, 680.69 expected, observed/expected ratio (o/e) 0.93, 90% interval 0.87 to 1. Synonymous variants: 292 observed, 307.04 expected, observed/expected ratio (o/e) 0.95, 90% interval 0.86 to 1.05.